LINC00839 (long independently transcribed non-coding RNA 839)
Gene: Long non-coding RNA gene on chromosome 10 (42,475,476 to 42,495,337, forward strand). Ensembl gene ENSG00000185904.
Diseases named in the same sentence as LINC00839 in open-access papers:
LINC00839 is named in the same sentence as 19 diseases in open-access papers, as found by Europe PMC text mining. Sharing a sentence is not in itself a finding about the gene and the disease. The quoted sentences say what the papers report.
breast cancer (8 papers, 2021 to 2024). A primary or metastatic malignant neoplasm involving the breast. "In the Risk Score prognostic model and lncRNA‐mRNA co‐expression network, AP001505.1 and LINC00839 are associated with many glucose metabolism‐related mRNAs, and also play an important role in the prognostic development of breast cancer." (PMID 36426411, 2023). "LINC00839 level is elevated in chemo-resistant breast carcinoma, and a higher level of LINC00839 is dramatically linked with inferior overall survival." (PMID 34965215, 2021). "The intricate regulatory network encompassing the Myc/LINC00839/LIN28B feedback loop presents a promising target for innovative therapeutic approaches in breast cancer treatment." (PMID 38495499, 2024). "LINC00839 is identified targeting specific tumor signaling pathways and exacerbates malignant features of several tumors, such as breast cancer and osteoblastoma." (PMID 37257820, 2023). "Linc00839 is located in the nucleus of breast cancer cells, promoting cell proliferation, invasion and migration." (PMID 36672487, 2023). "MIR200C and MIR141 host genes (MIR200CHG), endogenous bornavirus-like nucleoproteins (EBLN3P), and Linc00839 are closely related to a higher pathological grade, tumor size, and clinical stage of breast cancer patients." (PMID 36613528, 2022). "LINC00839 was reported to be upregulated in osteosarcoma and breast cancer; however, its expression pattern and functional roles in hepatocellular carcinoma remain to be elucidated." (PMID 34634995, 2021). "LINC00839 acts as an oncogenic gene and is significantly upregulated in human cancers including breast cancer and osteosarcoma." (PMID 34965215, 2021). "The expression of Linc00839 was activated by Myc and promoted proliferation and chemoresistance in breast cancer through binding with Lin28B via activation of the PI3K/AKT signaling pathway." (PMID 34589423, 2021). "LINC00839 has been studied in osteosarcoma and breast cancer, in which it is upregulated and functions as an oncogenic factor, but the role of LINC00839 has not been reported in HCC." (PMID 34634995, 2021). "Several studies described that LINC00839 was significantly elevated and could promote tumor progression in breast cancer, hepatocellular carcinoma, osteosarcoma, and neuroblastoma." (PMID 37257820, 2023). "Linc00839 was significantly upregulated both in tamoxifen-resistant breast cancer cells and ADR-resistant breast cancer cells, and the inhibition of Linc00839 enhanced apoptosis induced by paclitaxel by targeting the PI3K/AKT pathway in breast cancer cells." (PMID 36613528, 2022).
neuroblastoma (5 papers, 2023 to 2025). Neuroblastoma (NB) is the most common solid, extracranial childhood tumor. "The LINC00839 gene is most associated with nasopharyngeal carcinoma and neuroblastoma, while the LINC01605 gene is most associated with colorectal carcinoma and neoplasm." (PMID 41141624, 2025). "In xenograft mouse models, knockdown of LINC00839 resulted in diminished neuroblastoma growth 40, 41, and also led to extended survival time in mice compared to the control group 40." (PMID 38495499, 2024). "Mechanistically, LINC00839 plays an oncogenic role in neuroblastoma by upregulating NEUROD1 and GLUT1 expression through sponging miR-454-3p 41 and miR-338-3p 40, respectively." (PMID 38495499, 2024). "LINC00839 promotes the proliferation, migration, invasion, and apoptosis of neuroblastoma cells, indicating lower overall survival." (PMID 37529698, 2023). "LINC00839 could promote the progression of several cancers, including gastric cancer, neuroblastoma, colorectal cancer, and liver cancer." (PMID 37728407, 2023).
liver cancer (3 papers, 2022 to 2024). An epithelial or non-epithelial malignant neoplasm that arises from the liver. "Mechanistically, LINC00839 promotes liver cancer progression by interacting with multiple proteins primarily linked to metabolism and RNA transport, and further upregulates FMNL2 expression under hypoxic conditions." (PMID 38495499, 2024). "LINC00839 further overexpressed under hypoxia and promoted liver cancer cell proliferation, migration, and invasion." (PMID 36335129, 2022). "We examined the expression of LINC00839 in liver cancer cell lines and normal liver cell line using qPCR to validate its expression pattern." (PMID 36335129, 2022). "Our data revealed that LINC00839 was expressed at a higher level in liver cancer, and increased LINC00839 indicated poor prognosis, suggesting its tumor-promoting effect." (PMID 36335129, 2022). "LINC00839 expression was up-regulated in liver cancer tissues and cell lines, and the patients with high LINC00839 expression had shortened overall survival." (PMID 36335129, 2022). "To further investigate the oncogenic function of LINC00839 in liver cancer, we detected the location of LINC00839 in SNU-387 cells." (PMID 36335129, 2022). "So the exact function of LINC00839 in liver cancer should be investigated further." (PMID 36335129, 2022). "These experimental results indicated that LINC00839 may promote liver cancer progression by up-regulating FMNL2 expression." (PMID 36335129, 2022). "Functionally, this study demonstrated that LINC00839 promoted the proliferation, migration, and invasion of liver cancer cells under hypoxia, suggesting that LINC00839 may be a novel functional regulator of hypoxia-induced signaling." (PMID 36335129, 2022). "To estimate the function of LINC00839 on the malignant phenotypes of liver cancer cells under hypoxia, we constructed LINC00839-overexpressing lentivirus and LINC00839 shRNA lentivirus, and then established stably overexpressed or interfered SNU-387 cell lines." (PMID 36335129, 2022). "LINC00839 could promote hypoxia-mediated liver cancer progression, suggesting it may be a clinically valuable biomarker and serve as a molecular target for the diagnosis, prognosis, and therapy of liver cancer." (PMID 36335129, 2022). "Bioinformatic analysis showed that FMNL2 was up-regulated in liver cancer and correlated with patient unfavorable survival..Our data revealed FMNL2 may be a functional partner of LINC00839." (PMID 36335129, 2022). "Additionally, mechanistic investigations were performed to explore the potential mechanism of LINC00839 and its connection with FMNL2, which may provide a basis for clinical diagnosis and treatment of liver cancer." (PMID 36335129, 2022).
nasopharyngeal carcinoma (3 papers, 2021 to 2026). A carcinoma arising from the nasopharyngeal epithelium. "In another study, Zhang and colleagues found that LINC00839 promotes nasopharyngeal carcinoma invasion through the miR-454-3p/c-Met axis." (PMID 41141624, 2025). "However, the significance of LINC00839 in nasopharyngeal carcinoma (NPC) has yet to be illuminated, as well as its underlying mechanism." (PMID 34965215, 2021).
glioma (2 papers, 2023 to 2025). A benign or malignant brain and spinal cord tumor that arises from glial cells (astrocytes, oligodendrocytes, ependymal cells). "METTL3 activates the Wnt/β-catenin signaling pathway by promoting m6A methylation of LINC00839, thereby maintaining glioma stem cell stemness and inducing radioresistance." (PMID 41390674, 2025). "Next, CGGA dataset analysis results indicated that LINC00839 was significantly increased in recurrent glioma tissues." (PMID 37438359, 2023).
bladder cancer (1 paper, 2024). "Specifically, LINC00839 regulates SOX5 either directly or indirectly through the miR-142 axis, which increases the resistance of bladder cancer cells to gemcitabine by promoting autophagy." (PMID 39628486, 2024).
brain tumor (1 paper, 2023). "Mechanistically, METTL3-YTHDF2 mediated m6A modification elevated LINC00839 levels; LINC00839 functions as a scaffold for c-Src phosphorylates β-catenin at Y654, promoting Wnt signaling activation; β-catenin inhibitor treatment sensitizes brain tumor to radiotherapy." (PMID 37438359, 2023).
glioblastoma (1 paper, 2024). The most malignant astrocytic tumor (WHO grade IV). "The upregulated LINC00839 was associated with glioblastoma progression and radiation resistance by activating Wnt/β-catenin activation." (PMID 38688909, 2024).
lentivirus infection (1 paper, 2023). Virus diseases caused by the Lentivirus genus. "On the contrary, the proliferation, migration, and invasion activities of NPC cells were facilitated by overexpression of LINC00839 via lentivirus infection (all p < 0.01)." (PMID 37257820, 2023).
oral squamous cell carcinoma (1 paper, 2025). "In a previous study, we found that LINC00839 acts as an oncogene in oral squamous cell carcinoma (OSCC) through the miR-195-5p/cyclin E1 axis." (PMID 41141624, 2025).
Skin Cutaneous Melanoma (1 paper, 2025). "Increased LINC00839 gene expression was found in ovarian (OV) and Skin Cutaneous Melanoma (SKCM) cancers." (PMID 41141624, 2025).
tumor (8 papers, 2021 to 2025). "LINC00839 emerges as an oncogenic factor in tumorigenesis and exerts a positive influence on tumor-associated behaviors." (PMID 38495499, 2024). "The higher LINC00839 expression was positively associated with worse prognosis and bigger tumor size." (PMID 36335129, 2022). "Recent studies, including both in vitro and in vivo experiments, shows that LINC00839 plays a key oncogenic role in tumor progression." (PMID 38495499, 2024). "High expression levels of LINC00839 in tumor tissues indicated poor clinical outcomes with unfavorable clinicopathological features and prognosis in tumor patients, including lymph node metastasis, clinical stage, and overall and disease-free survival." (PMID 38495499, 2024). "In this review, we present a comprehensive summary of the most recent research progress elucidating the roles played by LINC00839 in the development of human neoplastic and non-neoplastic diseases." (PMID 38495499, 2024). "In vivo experiments employing mouse models further demonstrate that LINC00839 knockdown hampers tumor growth 32, 33 and curtails metastasis." (PMID 38495499, 2024). "Tumor sphere formation and stemness markers detection results suggested that β-catenin Y654 phosphorylation was essential for LINC00839 promoting GSC maintenance." (PMID 37438359, 2023). "Previous studies have proposed that LINC00839 is responsible for multiple cancer biological traits, including tumor growth, metastasis, and chemoresistance." (PMID 37257820, 2023). "The results showed that LINC00839 overexpression promoted tumor growth and radiation resistance; while celecoxib treatment efficiently suppressed tumor growth, whereas celecoxib and irradiation combinational treatment exhibited the strongest tumor inhibition." (PMID 37438359, 2023). "437–1507-nt fragment deletion significantly impaired the improved stemness of GSCs induced by FL LINC00839 transfection, as reflected by tumor sphere formation and stemness markers detection." (PMID 37438359, 2023). "To further clarify the oncogenic effect of LINC00839 on NPC tumor in vivo, we established stable LINC00839 knockdown SUNE-1 cells with shRNAs, which were then inoculated into nude mice to construct xenograft growth models." (PMID 37257820, 2023). "LINC00839 has been verified as a cancer-promoting factor in multiple malignancies, and its dysregulation is closely correlated with tumor initiation, development, and progression." (PMID 34965215, 2021). "LINC00839 may be involved in tumor development and progression by affecting various signaling pathways." (PMID 41141624, 2025). "Moreover, LINC00839 regulated tumor progression and development by mediating multiple vital biological processes, and tumor-related signaling." (PMID 38495499, 2024). "Notably, xenografts of LINC00839 knockdown group exhibited significantly reduced tumor growth rate, tumor volume, and tumor weight relative to scrambled control group (all p < 0.01)." (PMID 37257820, 2023). "In vivo, LINC00839 knockdown retards the tumor growth of NPC cells in the xenografted mice model." (PMID 34965215, 2021). "Furthermore, elevated LINC00839 expression indicates advanced clinicopathological features and foretells unfavorable prognoses, as validated by publications and comprehensive analyses of tumor types using TCGA datasets." (PMID 38495499, 2024). "Moreover, LINC00839's overexpression amplifies tumor growth and metastasis in vivo." (PMID 38495499, 2024). "Moreover, the inhibition of Linc00839 impeded tumor growth in nude mice." (PMID 36613528, 2022). "Taken together, our results showed that LINC00839, modified by METTL3-mediated m6A, exerts tumor progression and radiation resistance by activating Wnt/β-catenin signaling." (PMID 37438359, 2023). "Consistent with the role reported for these miRNAs in most previous studies, the miRNAs identified in our analysis as potential downstream targets of LINC00839 and LINC01605 may function as tumor suppressors in EC." (PMID 41141624, 2025).
tumor (continued). "Notably, LINC00839's engagement in pivotal signaling pathways, such as PI3K/AKT, OXPHOS, and Wnt/β-catenin, underscores its central position in maintaining cellular equilibrium and influencing tumor progression." (PMID 38495499, 2024). "Moreover, differential expression analysis suggested that the levels of LINC01116, LMO7‐AS1, KDM4A‐AS1, KMT2E‐AS1, KTN1‐AS1, LINC00839, DLX6‐AS1, UBL7‐AS1, and DDX11‐AS1 were notably up‐regulated in 77 ESCC samples or 162 EC tumor tissues than in 11 normal tissues." (PMID 36965032, 2023).
cancer (7 papers, 2021 to 2025). A tumor composed of atypical neoplastic, often pleomorphic cells that invade other tissues. "Impressively, reduced LINC00839 expression has been associated with heightened sensitivity to both drug and radiotherapy treatments, potentially offering a pathway to enhance the effectiveness of existing cancer therapeutic strategies." (PMID 38495499, 2024). "LINC00839 has garnered attention as a prospective therapeutic target in cancer therapy due to its intricate regulatory capabilities." (PMID 38495499, 2024). "The correlation between LINC00839 expression and clinical outcomes highlights its clinical utility in guiding therapeutic approaches for cancer patients." (PMID 38495499, 2024). "Kyoto Encyclopedia of Genes and Genomes (KEGG) analysis revealed that genes affected by endogenous LINC00839 silencing were enriched in cancer-related pathways, indicating a potential regulatory role of LINC00839 in NPC progression." (PMID 37257820, 2023). "LINC00839, a novel LncRNA, has been reported as an oncogene in several cancers, such as Osteosarcoma, Neuroblastoma, hepatocellular carcinoma." (PMID 35473680, 2022). "Notably, aberrant expression patterns of LINC00839 have been observed across diverse cancer tissues and cell lines." (PMID 38495499, 2024). "LINC00839, a novel LncRNA, is originally regarded as a cancer-promoting gene." (PMID 35473680, 2022). "LINC00839 was reported to be dysregulated in many kinds of cancer, including HCC39–42." (PMID 36335129, 2022). "Notably, the LINC00839-related model may also serve as a valuable tool for assessing the prognosis of cancer patients." (PMID 38495499, 2024). "In sum, LINC00839's intricate network of functions, spanning from regulatory scaffold to its role as a ceRNA and its impact on key signaling pathways, positions it as a promising therapeutic target for innovative cancer interventions aimed at tackling metastasis and refining treatment responses." (PMID 38495499, 2024). "Furthermore, elevated expression of LINC00839 has been significantly associated with unfavorable prognostic outcomes, such as overall survival (OS), disease-free survival (DFS), and advanced clinical features such as lymph node metastasis and advanced clinical stage, in several cancer types." (PMID 38495499, 2024).
LINC00839 also shares sentences with these, for which no sentence is quoted: osteosarcoma (4 papers); colorectal cancer (2); hepatocellular carcinoma (2); esophageal cancer (1); gastric cancer (1); Obesity (1).